OR52B4 (olfactory receptor family 52 subfamily B member 4)
Description:
Odorant receptor.
Synonyms: OR11-3
Tractability: Antibody: UniProt places it where antibodies can reach, with medium confidence; UniProt predicts a signal peptide or a membrane-spanning region; its Gene Ontology location is reachable by antibodies, with medium confidence.
Gene: Protein-coding gene on chromosome 11 (4,367,263 to 4,368,386, reverse strand). Ensembl gene ENSG00000221996.
Subcellular location: Cell membrane
Gene Ontology:
Molecular function: olfactory receptor activity; G protein-coupled receptor activity
Biological process: cognition; detection of chemical stimulus involved in sensory perception of smell; G protein-coupled receptor signaling pathway; nervous system process
Cellular component: plasma membrane; membrane
Genetic constraint (gnomAD): Loss-of-function variants: 0 observed, 0.16 expected, observed/expected ratio (o/e) 0, 90% interval 0 to 1.88. That is too few expected variants to judge how well the gene tolerates losing a copy. Missense variants: 443 observed, 402.3 expected, observed/expected ratio (o/e) 1.1, 90% interval 1.02 to 1.19. Synonymous variants: 182 observed, 148.47 expected, observed/expected ratio (o/e) 1.23, 90% interval 1.09 to 1.39.
Homologues: Orthologues: chimpanzee OR52B4 (97% identical), dog OR52B4 (86% identical), rabbit OR52B4 (85% identical), mouse Or52b4 (84% identical), rat Olr385 (80% identical), rat Or52b4 (77% identical), tropical clawed frog or52d1 (49% identical), tropical clawed frog or52al1 (45% identical). Paralogues in human: OR52B2 (56% identical), OR52H1 (53% identical), OR52E8 (52% identical), OR52B6 (51% identical), OR52D1 (50% identical), OR52E4 (50% identical), OR52E6 (49% identical), OR52E5 (49% identical), OR52K1 (48% identical), OR52J3 (47% identical), OR52K2 (47% identical), OR52E2 (47% identical), and 39 more.
Diseases named in the same sentence as OR52B4 in open-access papers:
OR52B4 is named in the same sentence as 1 disease in open-access papers, as found by Europe PMC text mining. Sharing a sentence is not in itself a finding about the gene and the disease.
OR52B4 shares sentences with these, for which no sentence is quoted: age-related macular degeneration (1 paper).